COL6A1 (collagen type VI alpha 1 chain)
Diseases named in the same sentence as COL6A1 in open-access papers (continued):
Sharing a sentence is not in itself a finding about the gene and the disease.
hypertrophic cardiomyopathy (2 papers, 2022 to 2025). A condition in which the myocardium is hypertrophied without an obvious cause. "During the rest phase (CT30 and CT34), ECM-receptor interaction (e.g., Tnxb, Col4a1, and Col6a1) was the most enriched pathway among genes downregulated in WT KPC mice, while hypertrophic cardiomyopathy (e.g., Des, Tnnc1, and Myl3) was the most enriched pathway among upregulated genes." (PMID 40349340, 2025).
hypospadias (2 papers, 2020 to 2023). Hypospadias is the displacement of the urethral meatus on the ventrum of the penis. "In this study, we determined the expression of collagen 1 (COL1A1) and COL6A1 in patients with hypospadias and associated them with the severity of penile curvature." (PMID 33261612, 2020). "Therefore, we determined the expression of collagen 1 (COL1A1) and COL6A1 in patients with hypospadias and associated them with the severity of penile curvature." (PMID 33261612, 2020). "Our previous study showed that the expression of COL1A1 and COL6A1 were significantly downregulated in the hypospadias patients with more severe chordee than the milder one (Indonesian)." (PMID 38041174, 2023). "Here, we are able to show downregulated COL1A1 and COL6A1 expression in hypospadias patients with moderate and severe penile curvature." (PMID 33261612, 2020). "We also investigated the significant difference in COL1A1 and COL6A1 expression among groups based on penile curvature in the hypospadias group." (PMID 33261612, 2020). "However, this study found decreased gene expression of COL6A1 in the hypospadias group compared to the control group." (PMID 33261612, 2020). "Aberrant COL1A1 and COL6A1 expression might affect abnormalities in darto tissue and penile curvature severity in hypospadias patients." (PMID 33261612, 2020).
leukemia (2 papers, 2024 to 2025). A malignant (clonal) hematologic disorder, involving hematopoietic stem cells and characterized by the presence of primitive or atypical myeloid or lymphoid cells in the bone marrow and the blood. "Leukemia patients with overexpression of ITGA2, COL6A1, cyclin D1, PKN1, PDGFRA, or F2R predict or have trends toward worse prognosis." (PMID 41203598, 2025). "Leukemia patients with overexpression of ITGA2, COL6A1, cyclin D1, PKN1, PDGFRA or F2R predicts or has trends toward worse prognosis." (PMID 39764125, 2024).
medulloblastoma (2 papers, 2007 to 2023). A malignant, invasive embryonal neoplasm arising from the cerebellum. "COL6A1 belongs to a collagen family, and are previously reported upregulated in metastases from medulloblastoma and cancers of the breast and prostate." (PMID 17201907, 2007).
neurofibroma (2 papers, 2021 to 2025). An intraneural or extraneural neoplasm arising from nerve tissues and neural sheaths. "We discovered that the three collagen VI genes (COL6A1, COL6A2, COL6A3) are abundantly expressed in neurofibroma fibroblasts." (PMID 33413690, 2021).
pancreatic adenocarcinoma (2 papers, 2023 to 2025). "TCGA analysis of TGF-β target genes (e.g., COL1A1, COL3A1, COL5A2, COL6A1, COL6A3, TIMP1, and CTGF) further identified overactivation of TGF-β signaling pathway in a broad spectrum of solid tumors, in particular in breast invasive carcinoma and pancreatic adenocarcinoma tissues." (PMID 37328484, 2023).
preeclampsia (2 papers, 2023 to 2025). Preeclampsia is a hypertensive disorder of pregnancy that is characterized by new-onset hypertension with proteinuria presenting after 20 weeks of gestation, and depending on mild or severe forms may initially present with severe headache, visual disturbances, and hyperreflexia. "In addition, these genes were elevated in the placentas of preeclampsia patients, including LRP1, COL6A1, ITGB2, and MMP3." (PMID 38003549, 2023).
viral infection (2 papers, 2023 to 2024). "The top 4 were “Cell matrix adhesion and organization” (COL6A1, COL6A2, COL18A1, JAM2, ADAMTS5 and POFUT2), “Immune/virus infection response” (MX1 and MX2), “Histone modification and chromatin remodeling” (NRIP1) and “Glycerolipid and lipid metabolism” (AGPAT3)." (PMID 38095646, 2023).
amebiasis (1 paper, 2020). A parasitic infectious disorder caused by amoebas. "Thirty-nine DEGs were present in both datasets, 13 of which, including COL6A1, COL6A2, and COL6A3, were enriched in ECM-receptor interaction, amebiasis, focal adhesion, protein digestion, and absorption pathways." (PMID 33680912, 2020).
amnesia (1 paper, 2022). Pathologic partial or complete loss of the ability to recall past experiences ( AMNESIA, RETROGRADE) or to form new memories ( AMNESIA, ANTEROGRADE). "In addition, and differently from wild-type mice, when tested in a habituation/dishabituation social task, Col6a1–/– mice did not display the characteristic decline in the time spent investigating a same-sex conspecific when becoming familiar, a pattern consistent with a social amnesia phenotype." (PMID 35946603, 2022).
aortic aneurysm (1 paper, 2023). A ruptured aneurysm located in the wall of the proximal portion of the descending aorta proceeding from the arch of the aorta. "Defects in the components of those pathways [Collagen Type IV Alpha 2 Chain (COL4A2), Collagen Type IV Alpha 1 Chain (COL4A1), Collagen Type VI Alpha 1 Chain (COL6A), Elastin (ELN)] were previously proposed to be associated with aortic aneurysm formation." (PMID 36922793, 2023).
aortic atherosclerosis (1 paper, 2020). A atherosclerosis that involves the aorta. "COL6A1 immunization in female mice interrupted this pathway with a tolerance-like response of decreased CD8+ T cell cytolytic activity and reduced IL-1β expression with decreased aortic atherosclerosis." (PMID 32373127, 2020).
arthrogryposis (1 paper, 2025). A rare, non-progressive congenital disorder characterized by multiple joint contractures which are present at birth. "None of the individuals with arthrogryposis caused by pathogenic variants in COL6A1, RYR1, or ZC4H2 achieved independent walking." (PMID 40443119, 2025).
B-cell lymphoma (1 paper, 2020). "Further analyses revealed that alteration of the expression of signature genes by ColXV was associated with B-cell lymphoma family and ECM remodeling, especially Bcl-2, Col1a1, Col6a1, MMP-2 and MMP-9." (PMID 32024006, 2020).
brain injury (1 paper, 2022). Acute and chronic (see also brain INJURIES, CHRONIC) injuries to the brain, including the cerebral hemispheres, CEREBELLUM, and brain STEM. "The association of COL6A1 function with angiogenesis under a hypoxic microenvironment is supported by results showing that COL6A1 is overexpressed in the cerebral cortex after hypoxic-ischemic brain injury." (PMID 35494018, 2022).
Chronic colitis (1 paper, 2025). A chronic inflammatory disease of the large intestine (colon, cecum and rectum). "Moreover, fibrosis in the DSS-induced chronic colitis model was alleviated, as evidenced by a reduction in collagen volume fraction, and a decrease in Col1a1 and Col6a1 expression." (PMID 41334589, 2025).
chronic obstructive pulmonary disease (1 paper, 2024). A chronic and progressive lung disorder characterized by the loss of elasticity of the bronchial tree and the air sacs, destruction of the air sacs wall, thickening of the bronchial wall, and mucous accumulation in the bronchial tree. "Data from the literature showed that the COL6A1 gene was upregulated in patients with nonemphysematous chronic obstructive pulmonary disease, so supporting the profibrotic mast cell phenotype, through collagen VI deposition." (PMID 39035772, 2024).
Cirrhosis (1 paper, 2023). A chronic disorder of the liver in which liver tissue becomes scarred and is partially replaced by regenerative nodules and fibrotic tissue resulting in loss of liver function. "Interestingly, the collagen gene cluster expressions were significantly associated with the presence of cirrhosis (p = 0.0085, 0.04, and 0.0283 for COL6A1, COL6A2, and COL6A3, respectively)." (PMID 38041174, 2023). "Interestingly, the collagen gene cluster expressions were significantly associated with the presence of cirrhosis (p = 0.0085, 0.04, and 0.0283 for COL6A1, COL6A2, and COL6A3, respectively) but not with the survival of BA patients and age at Kasai procedure." (PMID 38041174, 2023). "It is compatible with our findings that COL6A1, COL6A2, and COL6A3 expressions, not COL1A1, were strongly associated with the presence of cirrhosis." (PMID 38041174, 2023).
diffuse large B-cell lymphoma (1 paper, 2020). "Finally, certain lymphoproliferative diseases are also associated with expression of COL6A1, COL18A1, MMP3 and TIMP1, and a subset of patients with diffuse large B cell lymphoma and adverse prognosis show decreased expression of POSTN, SPARC, COL1A1, COL3A1,CSTK, MMP9 and LAMB3." (PMID 33379263, 2020).
Ehlers-Danlos syndrome (1 paper, 2021). The Ehlers–Danlos syndromes (EDS) are a clinically and genetically heterogeneous group of heritable connective tissue disorders (HCTDs) characterized by joint hypermobility, skin hyperextensibility, and tissue fragility. "Pathogenic variants in COL12A1, COL6A1, COL1A1, and COL5A1 have been described in individuals with different subtypes of the connective tissue disorders Ehlers-Danlos Syndrome and osteogenesis imperfecta." (PMID 33649486, 2021).
female infertility (1 paper, 2017). Diminished or absent ability of a female to achieve conception. "Crossing Antxr2−/− with Col6a1−/− mice leads to restoration of uterine structure and reversion of female infertility." (PMID 28604699, 2017).
frontotemporal dementia (1 paper, 2025). Frontotemporal dementia (FTD) comprises a group of neurodegenerative disorders, characterized by progressive changes in behavior, executive dysfunction and language impairment, as a result of degeneration of the medial prefrontal and frontoinsular cortices. "In C9ORF72-associated ALS/frontotemporal dementia models, dipeptide repeat expression triggered marked increases in ECM proteins such as collagen VI (COL6A1); overexpression of TGF-β1 or COL6A1 enhanced neuronal resistance to excitotoxicity, whereas their suppression exacerbated degeneration." (PMID 41373533, 2025).
gliosarcoma (1 paper, 2019). A rare histological variant of glioblastoma (WHO grade IV) characterized by a biphasic tissue pattern with alternating areas displaying glial and mesenchymal differentiation (WHO). "When compared to GBMs, gliosarcomas show up-regulation of some genes, ranging up to a 6-fold difference on a log2-scale and most top differentiating genes encode collagens (COL1A1, COL6A1, COL6A2, COL6A3, COL1A2, COL3A1)." (PMID 30818875, 2019).
glomerulosclerosis (1 paper, 2021). A hardening of the kidney glomerulus caused by scarring of the blood vessels. "Consistent with marked glomerulosclerosis in UNx-Renin mice, ECM-associated gene expression changes were more pronounced in UNx-Renin mice, in which additional markers of fibrogenesis were significantly upregulated, including Col1a1, Col3a1, Col6a1, Col6a2 and Mmp7." (PMID 34494644, 2021).
hip osteoarthritis (1 paper, 2012). "Together with previous studies showing accelerated hip osteoarthritis in Col6a1−/− mice, these findings suggest different roles for collagen VI at different sites in the body, consistent with clinical data." (PMID 22448243, 2012).
Hirschsprung disease (1 paper, 2022). Hirschsprung disease (HSCR) is a congenital intestinal motility disorder that is characterized by signs of intestinal obstruction due to the presence of an aganglionic segment of variable extent in the terminal part of the colon. "The modulation of COL6A1 and COL6A2 expression after RUNX1 silencing could explain the causal link between trisomy 21 and an increased incidence of Hirschsprung’s disease in DS." (PMID 35356434, 2022).
joint disease (1 paper, 2019). "Therefore, collagen dysfunction could lead to bone and joint disease including OA.COL24A1, COL5A2, COL3A1, COL6A1 are members of the collagen gene family." (PMID 30941059, 2019).
laryngeal carcinoma (1 paper, 2020). Carcinoma that arises from the laryngeal epithelium. "In our RNA-seq results, COL6A1, COL6A2, and COL6A3 were downregulated at mRNA levels in MYCT1 overexpressing laryngeal cancer cells (GSE123275)." (PMID 33680912, 2020). "At the mRNA level, Knockdown of MYCT1 significantly increased the COL6A1, COL6A2, and COL6A3 expression but MYCT1 decreased the COL6A2, and COL6A3 expression in laryngeal cancer cells (P < 0.01), respectively." (PMID 33680912, 2020). "In MYCT1-overexpressing laryngeal cancer cells, another 13 DEGs (GSE123275) were overlapped in the GSE6631 and TCGA datasets, where COL6A1, COL6A2, and COL6A3 were also present." (PMID 33680912, 2020). "This implies that COL6A1, COL6A2, and COL6A3 are crucial in laryngeal cancer." (PMID 33680912, 2020).
leiomyosarcoma (1 paper, 2024). An uncommon, aggressive malignant smooth muscle neoplasm, usually occurring in post-menopausal women. "Furthermore, in TCGA-SARC, COL6A1 gene expression was associated with reduced long-term survival among liposarcoma patients, where tumor COLVI expression levels are similar to those in UPS, but not among leiomyosarcoma patients, where tumor COLVI levels are significantly lower." (PMID 38652549, 2024).
mesenchymal tumors (1 paper, 2023). "The combination of the expression of the genes PLAU, LAMB1, COL6A1, and TGFBI classified correctly the majority of mesenchymal tumors." (PMID 38031074, 2023).
multiple system atrophy (1 paper, 2013). Multiple system atrophy (MSA) is a neurodegenerative disorder characterized by autonomic failure (cardiovascular and/or urinary), parkinsonism, cerebellar impairment and corticospinal signs with a median survival of 6-9 years. "A decrease in collagen IV is observed in Multiple System Atrophy, and the reduction of COL6A1 has been reported in AD." (PMID 23497022, 2013).
oral diseases (1 paper, 2024). "COL6A1 is a type VI collagen component, while MMP3 is involved in matrix degradation in oral diseases." (PMID 39092323, 2024).
oral mucositis (1 paper, 2025). Inflammation of the mucous membranes of any of the structures in the mouth. "As the only exception, three putative autoantibodies were significantly higher in “mucosal toxicity” compared with “no toxicity” (PCBP2, COL6A1, SEMG1), referring to patients developing oral mucositis." (PMID 40449958, 2025).
pancreatic ductal adenocarcinoma (1 paper, 2024). An infiltrating adenocarcinoma that arises from the epithelial cells of the pancreas. "Analysis of TCGA PanCancer RNA sequencing data revealed that, like in sarcomas, COL6A1, COL6A2, and COL6A3 are highly expressed in pancreatic ductal adenocarcinoma (PDAC)." (PMID 38652549, 2024).
progressive myoclonus epilepsy (1 paper, 2020). A rare group of disorders characterized by the development of myoclonic and tonic-clonic epileptic seizures associated with progressive degeneration of the nervous system. "Mutations in COL6A2 were linked to progressive myoclonus epilepsy 73, and COL6A1 was reported within a set of genes that are upregulated in the human cerebral cortex with respect to non‐human primates, indicating a human‐specific role of this gene in brain development and evolution." (PMID 32207244, 2020).
scleroderma (1 paper, 2023). Scleroderma is a rare autoimmune connective tissue disorder characterized by abnormal hardening of the skin and, sometimes, other organs. "In accordance with the disease hallmarks, subtypes of collagen (COL1A1, COL6A1) were more highly expressed in scleroderma." (PMID 37443817, 2023).
skin aging (1 paper, 2015). The gradual irreversible changes in structure of skin that occur as a result of the passage of time.. "Indeed, we detected a set of metallo-proteinases (MMP2, MMP14), collagens (e.g. COL6A1, COL3A1, COL5A1 and others) and elastin (ELN), which showed a significant longitudinal change in expression in addition to being closely correlated to skin aging." (PMID 25977295, 2015).
tubulointerstitial nephritis (1 paper, 2020). "Notably, the mix of ADAMTS5-affected matrix proteins was enriched in basement-membrane components including laminins (LAMA/LAMB/LAMC), collagen-6 (COL6A1/A2), collagen-12 (COL12A1), AGRN, nidogen-1 (NID1), and TINAG (tubulointerstitial nephritis Ag)." (PMID 32917786, 2020).